XRCC6P2 (X-ray repair cross complementing 6 pseudogene 2)
Gene: Processed pseudogene on chromosome X (150,231,075 to 150,232,896, reverse strand). Ensembl gene ENSG00000234825.
Diseases named in the same sentence as XRCC6P2 in open-access papers:
XRCC6P2 is named in the same sentence as 2 diseases in open-access papers, as found by Europe PMC text mining. Sharing a sentence is not in itself a finding about the gene and the disease. The quoted sentences say what the papers report.
cancer (1 paper, 2023). A tumor composed of atypical neoplastic, often pleomorphic cells that invade other tissues. "Some are known to be tumor suppressor genes (OPCML-IT2), to be related to resistance to cancer therapies (RAC1P3), or to be involved in several cancer processes such as genome stability (XRCC6P2), tumor growth and metastasis (MIR602) and regulation of gene transcription (NME2P2)." (PMID 36647008, 2023).
XRCC6P2 also shares sentences with these, for which no sentence is quoted: tumor (1 paper).